INS (insulin)
Diseases named in the same sentence as INS in open-access papers (continued):
Sharing a sentence is not in itself a finding about the gene and the disease.
metabolic syndrome (continued). "These hormonal alterations may lead to reactive insulin hypersecretion, and increasing visceral obesity and sarcopenia, resulting to dyslipidemia, hypertension and DMT2." (PMID 21542944, 2011). "The myocardial metabolism findings were similar regardless of whether we used the modified definition for MC or the traditional NCEP/ATP-III criteria for metabolic syndrome (i.e. excluding fasting insulin and BMI criteria)." (PMID 22151886, 2011). "The effect of variants on IL-18 levels and their association with insulin levels and sensitivity suggests that insulin sensitivity and metabolic syndrome may have a genetic basis." (PMID 20227263, 2011). "Post-streptococcal anti-PDI antibodies are associated with metabolic syndrome regardless of fasting insulin and CRP levels." (PMID 21949836, 2011). "Importantly, the anti-PDI - metabolic syndrome association remained significant after adjusting for CRP and fasting insulin." (PMID 21949836, 2011). "In addition, metformin was superior to E2-P in increasing insulin sensitivity, while decreasing dyslipidemia, anovulation, body adiposity, and the pro-inflammatory state associated with PCOS." (PMID 21899727, 2011). "Given the physiological outcomes associated with the metabolic syndrome, objective outcome measures such as lipoprotein profiles, circulating levels of glucose and insulin, and anthropometric measures are consistent across studies of the metabolic syndrome, which allows for comparison among studies." (PMID 21773016, 2011). "We hypothesized that the MA compared to NHW would exhibit lower initial insulin sensitivity and greater dyslipidemia, but would experience intervention-induced improvements in these parameters." (PMID 21364957, 2011). "We have therefore extended our previous mouse studies to investigate central components of the metabolic syndrome, notably growth, cardiovascular phenotype, glucose and insulin homeostasis, adiposity and fat gene expression patterns in mouse offspring at 1 year of age." (PMID 22194901, 2011). "We studied the effects of whole grain and low insulin response grain products, fatty fish, and bilberries on glucose metabolism, plasma fatty acids and lipidomic profile in individuals with features of the metabolic syndrome." (PMID 21901116, 2011). "In addition, serum adiponectin is also considered to be an important modulator of insulin sensitivity and dyslipidemia." (PMID 21586120, 2011). "Daily supplementation with 300 mg RIAA and 1500 mg PAC in addition to lifestyle modification including dietary alteration reduces serum TG, TG : HDL, and fasting insulin significantly more than diet and lifestyle modification alone in patients with features of the metabolic syndrome." (PMID 20721358, 2010). "The addition of certain phytochemicals such as RIAA from hops and PAC from acacia to dietary and lifestyle modification has the potential to more favorably modulate insulin signaling and to decrease the deleterious effects of lipotoxicity which characterize metabolic syndrome." (PMID 20721358, 2010). "Furthermore, the PPARα agonists gemfibrozil and fenofibrate improve dyslipidemia and insulin sensitivity in humans." (PMID 20825652, 2010). "Although it remains unclear whether SOCS1 polymorphisms modify SOCS1 expression in the liver and SOCS1 polymorphisms influence insulin sensitivity and lipid metabolism, SOCS1 polymorphisms might be associated with metabolic syndrome in humans." (PMID 20862390, 2010). "Since subjects with metabolic syndrome often have elevated levels of glucose and insulin, it may contribute to the progression of atherosclerosis among them." (PMID 20727144, 2010). "Overall, the effects of PPAR agonists on AMPK-mediated metabolic functions may contribute to the recovery of insulin sensitivity or treatment of metabolic syndrome." (PMID 20814441, 2010).
metabolic syndrome (continued). "Currently, insulin sensitizing drugs, such as metformin and thiazolidinediones, are part of the treatment of practically any type 2 diabetic patient and can also be used in patients with the metabolic syndrome." (PMID 22615610, 2010). "Thus, the dietary factor/component (for example carbohydrate restriction) that lowers serum leptin can also improve several indicators of metabolic syndrome such as circulating triacylglycerol and insulin and fat mass." (PMID 19144201, 2009). "We found that these compounds substantially elevated insulin secretion, which might subsequently attenuate dyslipidemia in CA or EA treated diabetic mice via improving lipid metabolism." (PMID 19678956, 2009). "By turning down the inflammatory and oxidative processes, Mediterranean diet may also lessen the -derived from liver lipid storage- hepatic insulin resistance and the raise of endogenous glucose production, which in turn may accompany metabolic syndrome." (PMID 19642977, 2009). "Mainly present in genes of lipid metabolic pathways (APOA5, APOB, APOC3 and LPL), the higher frequency of risk alleles in Puerto Ricans has been associated previously in other populations with unfavorable lipid profile and insulin response, cardiovascular conditions and metabolic syndrome." (PMID 19682384, 2009). "However, the atypical AP clozapine does induce a metabolic syndrome including weight gain, glucose tolerance and insulin sensitivity via alteration of glucose metabolism in rats." (PMID 19758435, 2009). "It is characterized by reduced response to insulin, central obesity, and dyslipidemia." (PMID 19822001, 2009). "Agonists of peroxisome proliferator-activated receptors (PPARα, PPARγ, PPARδ) regulate lipoprotein metabolism, fatty acid oxidation, glucose homeostasis and inflammation, and therefore are used as anti-diabetic drugs for treatment of dyslipidemia and insulin insistence." (PMID 19636418, 2009). "Furthermore, the PRO diet produced greater improvement in features of dyslipidemia and post-prandial INS response." (PMID 18990242, 2008). "Subjects with the metabolic syndrome according to WHO definition had significantly higher insulin levels and Framingham risk scores than subjects without the metabolic syndrome." (PMID 18088443, 2007). "GH plus PIO may have added benefit on body composition and insulin sensitivity in the metabolic syndrome." (PMID 17479164, 2007). "The pathogenic mechanisms that impair insulin action in these tissues, and the factors responsible for the development of the Metabolic Syndrome trait cluster have not been fully elucidated." (PMID 16854242, 2006). "Interestingly, overexpression of resistin led to an inhibition of the production of IL-10, which limits inflammatory responses and promotes insulin sensitivity and is also down-regulated in metabolic syndrome." (PMID 16854242, 2006). "There is also considerable doubt whether subgroup of patients with metabolic syndrome are indeed insulin resistant." (PMID 17078884, 2006). "Telmisartan, an antihypertensive agent with evidence of partial peroxisome proliferator-activated receptor activity-gamma (PPARγ) activity, may improve insulin sensitivity and lipid profile in patients with metabolic syndrome." (PMID 15892894, 2005). "This study demonstrated that (a) PPARγ agonists improved insulin sensitivity and ameliorated dyslipidemia in HF fed rats and ZDF rats, which were correlated with serum adiponectin; (b) Serum adiponectin was positively correlated with adipose FABP3 mRNA in GI262570-treated rats." (PMID 15491498, 2004). "Thus, the reductions in VAT we report may have contributed to reducing hepatic steatosis, systemic inflammation and dyslipidemia, and improving multi‐tissue insulin sensitivity and vascular function." (PMID 41251158, 2026).
metabolic syndrome (continued). "Interestingly, our findings align with previous studies demonstrating that FA can ameliorate diabetic conditions by enhancing insulin signaling, improving kidney and liver function, reducing dyslipidemia, and modulating key diabetogenic enzymes in diabetic rat models." (PMID 41142063, 2025). "Furthermore, in clinical studies, high adherence to the MedDiet improved multiple metabolic syndrome components, and MedDiet interventions have demonstrated significant drops in blood pressure (≈5 mmHg) and fasting insulin, leading to improved HOMA-IR and regression of metabolic syndrome in adults." (PMID 41003008, 2025). "Tangeretin-reduced oxidative stress in the present study may involve at least two mechanisms; a direct effect, tangeretin exhibits its antioxidant capacity, and an indirect impact, tangeretin improves insulin sensitivity and dyslipidemia and then reduces oxidative stress." (PMID 40141836, 2025). "Notably, several researches indicate that MBX-8025 is capable to enhance insulin sensitivity, reverse dyslipidemia, mitigate hepatic accumulation of lipotoxic lipids, and ameliorate NASH pathology in diet-fed atherosclerotic obese diabetic mice in a mouse model of obesity, dyslipidemia and diabetes." (PMID 40655103, 2025). "A consequence of the lifestyle common in affluent societies is an increase in body weight, which over a long time may lead to metabolic syndrome and T2DM; the latter is caused by a relative insulin deficiency due to pancreatic β-cell dysfunction and insulin resistance in multiple organs." (PMID 40362870, 2025). "Also, it helps improve insulin sensitivity and treats dyslipidemia." (PMID 40100371, 2025). "Interestingly, recent studies have suggested that comorbidities such as hypercholesterolemia, prediabetes, and metabolic syndrome may impair cardioprotective interventions, including insulin treatment and ischemic pre- and postconditioning." (PMID 40722907, 2025). "These outcomes, although associative and not causal, align with existing mechanistic and clinical data suggesting that the bioactive constituents of quince, olive leaves and amaranth may modulate key metabolic pathways involved in dyslipidemia, insulin sensitivity, and systemic inflammation." (PMID 41011029, 2025). "Moreover, in obese nondiabetic adults with metabolic syndrome, even higher doses of CrPic (1000 μg day−1 for 16 weeks) did not improve insulin sensitivity, serum lipids, or other cardiometabolic risk markers." (PMID 41373659, 2025). "These dyslipidemias may affect insulin sensitivity, thereby exacerbating the condition of GDM." (PMID 41323972, 2025). "Fourth, the present study lacks data on several covariates that could potentially influence dyslipidemia, such as dietary patterns, thyroid hormones, visceral fat indicator (e.g., waist circumference), and an insulin resistance marker (e.g., insulin resistance homeostasis model assessment)." (PMID 40495241, 2025). "While we have adjusted for several confounders, including gender, age, body mass index (BMI),dyslipidemia, smoking, history of atrial fibrillation, peripheral vasculardisease, coronary artery disease, and insulin treatment, it is important to notethat unknown confounders may still exist." (PMID 40026524, 2025). "Studies have also demonstrated that PEDF possesses insulin-sensitizing effects in the liver and adipose tissues and exhibits anti-inflammatory, anti-thrombogenic, and vasculoprotective properties in vivo, offering protection against metabolic syndrome and cardiovascular diseases." (PMID 41027922, 2025). "Furthermore, dyslipidemia may compromise pancreatic functions and those of other organs by impairing both insulin secretion and peripheral insulin sensitivity." (PMID 40868893, 2025). "Moreover, climbing stairs might enhance basal metabolic rate and insulin sensitivity, leading to increased caloric expenditure and a reduction in visceral fat, as well as protect against the metabolic syndrome." (PMID 40843206, 2025).
metabolic syndrome (continued). "HFD-fed mice exhibited increased fasting glucose, impaired glucose and insulin tolerance, dyslipidemia, elevated leptin, β-amylase, hepatic mitochondrial oxidative stress, and liver enzymes, alongside decreased fasting insulin, β-cell activity, adiponectin, and islet insulin secretion." (PMID 40726918, 2025). "Interestingly, the activity of central regulators of lipid homeostasis, SREBPs, has been implicated in the development of MASLD, as it can be triggered by excessive caloric intake, insulin resistance, or endoplasmic reticulum stress, contributes to the development of metabolic syndrome and MASLD." (PMID 40559416, 2025). "By the end of the dietary protocol, mice showed increased weight gain and developed insulin and glucose intolerance, as well as increased levels of circulating insulin, TAGs, and glucose, corroborating that our dietary protocol successfully induced metabolic syndrome symptoms." (PMID 38184590, 2024). "Furthermore, patients with metabolic syndrome present with a lower amount of EVs with medium size, which was related to fasting insulin levels accompanied by consequences of insulin sensitivity, while studies show leptin to mediate the release of EVs from breast cancer cells." (PMID 39203770, 2024). "We could not find any evidence for this causal link in the present study, which contradicts findings showing that FMT from lean healthy donors improves the insulin sensitivity of subjects with metabolic syndrome that were assumed to be driven by the recipient baseline fecal microbiota signature." (PMID 39624839, 2024). "However, CaMKK2 inhibition may offer a significant improvement over androgen deprivation therapy as it not only prevents prostate cancer progression but also protects against metabolic syndrome, improves insulin sensitivity, and increases bone mass." (PMID 39268917, 2024). "As a valid surrogate for insulin sensitivity that includes both laboratory and anthropometric measurements, METS-IR has been proposed as a tool to identify individuals at an elevated risk of developing T2DM, metabolic syndrome, and other cardiovascular diseases (CVDs) at an early age." (PMID 39015177, 2024). "Moreover, dyslipidemia and insulin use were less prevalent in populations with high calcium intake." (PMID 38613076, 2024). "It has been proposed that lactisole inhibition of horse gut-expressed sweet taste receptor may have the potential for the inhibition of intestinal glucose uptake and can be used as a therapeutic strategy for the management of insulin dysregulation in horses with metabolic syndrome." (PMID 38410741, 2024). "Studies have suggested that there is a potential association between HUA and several conditions, such as elevated glucose levels, reduced insulin sensitivity, irregular lipid profiles, and metabolic syndrome, which may contribute to the onset of diabetic neuropathy." (PMID 39072278, 2024). "Thus, when confined, fed hypercaloric and sugar-rich diets, and allowed access to pastures with high non-structural carbohydrate content, metabolic (obesity and hyperlipemia), endocrine (metabolic syndrome and insulin dysregulation) and clinical (laminitis) disturbances develop." (PMID 38396558, 2024). "Furthermore, evidence indicates that sucralose intake may impair insulin sensitivity, a key factor in regulating lipid metabolism, thus exacerbating dyslipidemia." (PMID 39015535, 2024). "Our group has reported that in the metabolic syndrome model (30% sucrose intake), the fenofibrate therapy significantly reduced Ang II concentration and downregulated the Ang II signaling pathway, in addition to decreasing myocardial fibrosis and restoring local insulin sensitivity." (PMID 39273057, 2024).
metabolic syndrome (continued). "Also consistent with our result, different randomized interventional studies have demonstrated the benefits of MD, compared to other nutritional interventions on insulin-resistant improvement in obese and overweight patients and in patients with metabolic syndrome and NAFLD." (PMID 39519621, 2024). "Accordingly, while LL consumption may show potential for improving insulin sensitivity against HFD-induced metabolic syndrome by regulating pancreatic insulin secretion, the current results did not reveal statistically significant differences in serum glucose levels." (PMID 39770882, 2024). "Therefore, eGDR based on Williams would lend itself well to evaluating the effects of interventions, which may improve insulin sensitivity and might be a better choice than a categorical variable such as the metabolic syndrome." (PMID 38702680, 2024). "However, triple therapy may be preferable due to its lower incidence of hypoglycemic episodes, lower cost, and improvement in dyslipidemia compared to dual OHA plus Insulin therapy." (PMID 39570934, 2024). "Based on prior research and our study findings, we suggest that insulin and its metabolism serve as a significant mediator in the relationship between phthalate metabolites and the occurrence of gallstones, as opposed to oxidative stress, inflammation, body composition, and metabolic syndrome." (PMID 38903577, 2024). "Metabolic syndrome (MetS) represents an assembly of functional disturbances including obesity, increased waist circumference, increased insulin levels/blood glucose, hypertension and/or low high-density lipoprotein (HDL)/high triglycerides (TG) count." (PMID 37393272, 2023). "As lipase is suppressed by insulin, insulin insufficiency or resistance may result in dyslipidemia." (PMID 37143509, 2023). "IR is characterized by insulin-mediated blood glucose management disorders, blood glucose utilization disorders, abnormal lipid accumulation, and increased lipid decomposition activities in adipocytes, which can be called insulin resistance syndrome or metabolic syndrome." (PMID 37056675, 2023). "In case of predicting the insulin levels, the most informative features were the presence of metabolic syndrome for all the time-points, BMI and the MISI score for time-points 2–6 and whether the individual was taking glucose lowering medication for time-points 2–4." (PMID 37498860, 2023). "In addition, renal protection may occur via neurogenic anti-inflammatory effects and secondary to dyslipidemia correction and increased plasma insulin levels that are mediated by ACTH." (PMID 36969288, 2023). "We found a significant association between insulin peak and triglycerides: this association was expected because hypertriglyceridemia is a key criterion for the diagnosis of metabolic syndrome, but we were surprised not to confirm a significant p-value for the remaining lipid profile." (PMID 37754306, 2023). "Our systematic review suggests that caffeine optimized the hepatic function in the setting of metabolic syndrome through increasing cholesterol uptake from the serum, decreasing serum total bilirubin and potentially attenuating gluconeogenesis through the decrease in insulin resistance." (PMID 36740696, 2023). "Indeed, the relationship with metabolic syndrome severity and EVs highlight those with healthier states may respond to insulin by reducing EVs to a greater extent." (PMID 36597186, 2023). "Although the exact mechanism is unknown, increased adiposity has been shown to disrupt the hypothalamic–pituitary–ovarian axis and steroidogenic activity in the ovary, through decreased insulin sensitivity, leading to metabolic syndrome and increased inflammation." (PMID 37766680, 2023).